GSK3B (glycogen synthase kinase 3 beta)
Diseases named in the same sentence as GSK3B in open-access papers (continued):
Sharing a sentence is not in itself a finding about the gene and the disease.
thyroid (2 papers, 2025 to 2026). "In our study, the results indicated TRIM47 endorses thyroid tumorigenesis via the down-regulation of ADARviaTRIM47/ADAR axis as well, which involved GSK-3β mediated phosphorylation." (PMID 40618019, 2025).
ulcerative colitis (2 papers, 2022 to 2024). An inflammatory bowel disease involving the mucosal surface of the large intestine and rectum. "In line with the present work, GSK-3β was reported to be activated in ulcerative colitis, where it positively regulated NF-κB, which then controls pro-inflammatory mediators like TNF-α." (PMID 36386153, 2022). "In addition, rutin can alleviate DSS-induced ulcerative colitis in mice through p38/MK2 and PI3K/Akt/GSK3β/NF-κB pathways, maintaining intestinal integrity and balancing the cytokine ratio." (PMID 39519671, 2024).
vitamin B deficiency (2 papers, 2019 to 2020). A condition due to deficiency in any member of the vitamin B complex. "Some studies have found that vitamin B deficiency can lead to low levels of cytosine methylation in the GSK-3β promoter region and hence the GSK-3β overexpression." (PMID 31093272, 2019). "About that, it was reported that vitamin B deficiency can lead to low levels of cytosine methylation in the GSK-3β promoter region and hence modulate the GSK-3β overexpression." (PMID 33114170, 2020).
Waardenburg syndrome type 2 (2 papers, 2020). Waardenburg syndrome type 2 (WS2) is an autosomal dominant subtype of Waardenburg syndrome (WS), characterized by varying degrees of deafness and pigmentation anomalies of eyes, hair and skin, but without dystopia canthorum. "The exchange of this amino acid residue for a proline due to a mutation in the MITF gene is the cause of the Waardenburg syndrome type II and reveals the central role displayed by GSK-3β in the regulation of pigmentation." (PMID 32674468, 2020). "The GSK3β-mediated phosphorylation at Ser298 increases the binding activity of MITF; of note, this is a feature of the Waardenburg syndrome type II, a rare genetic disease characterized by pigmentation defects." (PMID 33332393, 2020).
abdominal aortic aneurysm (1 paper, 2023). Enlargement and ballooning of the vessel that supplies arterial blood to the abdomen, pelvis and legs. "There is evidence of increased GSK3β phosphorylation in abdominal aortic aneurysms (AAAs)." (PMID 36669494, 2023).
adamantinoma (1 paper, 2015). A low grade malignant neoplasm arising from the long bones. "The mandibular benign adamantinomas showed immunoreactivity to both GSK3α and GSK3β (e, f)." (PMID 25645517, 2015).
adenomyosis (1 paper, 2024). The growth of endometrial tissue inside the muscular wall of the uterine corpus. "In addition, it identifies promising future targets for the development of adenomyosis treatment, such as m6A, GSK3β, sphks, etc." (PMID 39595579, 2024). "Furthermore, as a common upstream signaling molecule, GSK-3β may influence the treatment of adenomyosis through the modulation of its signaling pathway." (PMID 39595579, 2024). "Key downstream targets of GSK-3β, including vimentin, Bcl-2, snail, and α-SMA, are highly expressed in adenomyosis lesions." (PMID 39595579, 2024). "In summary, GSK-3β serves as a key link between proteins such as PI3K/AKT and Bcl-2, making it a potential target for the treatment of adenomyosis." (PMID 39595579, 2024).
Adenovirus Infection (1 paper, 2012). "We next asked whether epithelial susceptibility to adenovirus infection was increased upon GSK3β inhibition." (PMID 23166798, 2012).
advanced heart failure (1 paper, 2025). Patients with advanced heart failure have severe limitations, experiences symptoms even while at rest and are mostly bedbound patients. "The elevated S-nitrosylation levels of tropomyosin and GSK-3β in HFrEF are associated with systolic dysfunction in advanced heart failure." (PMID 40867518, 2025).
age (1 paper, 2024). A temporal measurement of the time period elapsed since an identifiable point in the life cycle of an organism. "Age-related PD-like deficits can also be induced by neuron-specific seipin KO as reflected by impaired motor coordination, α-synuclein fibril formation in dopaminergic neurons and their progressive decline, as well as increased p-GSK3β-Tyr216 and decreased p-GSK3β-Ser9 levels in aging mice." (PMID 39125833, 2024).
airway hyperresponsiveness (1 paper, 2022). "Epithelial CAR depletion also promoted smooth muscle cell proliferation mediated by GSK3β and TGF-β, basal matrix production and airway hyperresponsiveness." (PMID 36302767, 2022).
alcohol use disorder (1 paper, 2022). "Subjects with comorbid MDD/SUD had significantly lower levels of Gsk3β expression compared to control subjects (p < 0.003; adjusted for significant effects of ZT time, duration of alcohol use disorder, and suicide)." (PMID 36161151, 2022).
allergic asthma (1 paper, 2023). A asthma with a basis in a pathological type I hypersensitivity reaction. "GSK-3β functions in diverse cellular processes that have been implicated in a range of human pathologies, including allergic asthma." (PMID 35831673, 2023).
allergic disease (1 paper, 2014). An immune response that occurs following re-exposure to an innocuous antigen, and that requires the presence of existing antibodies against that antigen. "These novel findings suggest that GSK3β may be a useful target in developing strategies designed to increase the stability and function of Treg cells for treating allergic diseases." (PMID 24667347, 2014).
allergic rhinitis (1 paper, 2024). Inflammation of the nasal mucous membranes caused by an IgE-mediated response to external allergens. "On the other hand, M2 polarization of macrophages was facilitated by miR-214 via targeting of the glycogen synthase kinase 3 beta (GSK3B) enzyme in a model of allergic rhinitis." (PMID 38339220, 2024).
anaplastic large cell lymphoma (1 paper, 2019). Anaplastic large cell lymphoma (ALCL) is a rare and aggressive peripheral T-cell non-Hodgkin lymphoma, belonging to the group of CD30-positive lymphoproliferative disorders, which affects lymph nodes and extranodal sites. "Activation of PI3K-AKT signaling has been found to enhance GLI1 protein stability in pancreatic and ovarian cancer and in anaplastic large cell lymphoma (ALCL), where AKT1 counteracts the inhibitory effect of GSK3β on GLI1." (PMID 31244888, 2019).
anaplastic oligodendroglioma (1 paper, 2011). A WHO grade III oligodendroglioma with focal or diffuse malignant morphologic features (prominent nuclear pleomorphism, mitoses, and increased cellularity). "In summary, the differences in subcellular localization of CDC2 and GSK3β noted in GBM and anaplastic oligodendroglioma suggests that in those cells these with distinct subcellular localization, these molecules may have unique functions." (PMID 21660227, 2011).
aneurysm (1 paper, 2022). Bulging or ballooning in an area of an artery secondary to arterial wall weakening. "Among them, six hub genes might be the core genes for the rupture of aneurysms, including APP, JUN, GSK3B,ErbB2, PPBP and THBS1." (PMID 35432454, 2022). "GSK3b may play a negative role in the rupture pathogenesis of aneurysms." (PMID 35432454, 2022).
arrhythmogenic right ventricular cardiomyopathy (1 paper, 2025). "The following search queries were used: (arrhythmogenic cardiomyopathy OR arrhythmogenic right ventricular cardiomyopathy OR ARVC or ACM) AND (SB216763 OR GSK3β OR SB485232 OR tideglusib)." (PMID 39392548, 2025).
Auditory hallucination (1 paper, 2025). Perception of sounds without auditory stimulus. "We also identified the GSK3B gene as being associated with auditory hallucinations through gene set analysis, particularly in the regulation of biogenesis." (PMID 40943654, 2025).
autoimmune conditions (1 paper, 2020). "Publication bias exists to some degree as there are either reports of GSK3β inhibitors as positive regulators of the immune response against tumors or negative regulators of the immune response in autoimmune conditions." (PMID 32850361, 2020).
autoimmune hepatitis (1 paper, 2026). Hepatitis caused by autoantibodies. "Additionally, vitexin formed hydrogen bonds with AMP-activated protein kinase, modulating the downstream AKT/GSK-3β/Nrf2 pathway and attenuating of autoimmune hepatitis." (PMID 41511947, 2026).
Aymé-Gripp syndrome (1 paper, 2023). "In fact, mutations affecting the GSK3β phosphorylation sites of “large MAF” factors result in pathologies like Aymé-Gripp syndrome (MAF), Multicentric Carpotarsal Osteolysis (MAFB), and Retinitis Pigmentosa (NRL)." (PMID 36380627, 2023).
Azoospermia (1 paper, 2014). Absence of any measurable level of sperm,whereby spermatozoa cannot be observed even after centrifugation of the semen pellet. "Given the importance of the Wnt signaling pathway in male reproduction especially spermatogenesis, this study was designed to evaluate the expression of GSK3-β the key regulator of this signaling pathway and its presumptive role in azoospermia." (PMID 25031575, 2014). "Quantitative real-time RT-PCR analysis of normal (healthy), obstructive azoospermia and non-obstructive azoospermia testicular samples were performed for GSK3-β gene expression." (PMID 25031575, 2014). "Expression of GSK3-β was down-regulated in non-obstructive azoospermia (3.10±0.19) compared with normal (7.12±0.39) and obstructive azoospermia (6.32±0.42) groups (p=0.001)." (PMID 25031575, 2014). "Expression of GSK3-β was down-regulated in non-obstructive azoospermia (3.10±0.19) compared to normal (7.12±0.39) and obstructive azoospermia (6.32±0.42) groups." (PMID 25031575, 2014).
benign tumors of the mouth (1 paper, 2015). "Although the overexpression of GSK3β and the mild expression of GSK3α were found in various types of cancer and benign tumors of the mouth, the expression was mainly detected in OSCC." (PMID 25645517, 2015).
bone osteosarcoma (1 paper, 2025). A usually aggressive malignant bone-forming mesenchymal neoplasm arising from the bone. "Furthermore, we further determine the effects of STYK1 on GSK3β sequestration in ATG7–/– human bone osteosarcoma epithelial cells (U2OS cell line)." (PMID 40588478, 2025).
bone sarcoma (1 paper, 2015). A sarcoma that arises from the bone. "Stimulation of Wnt/β-catenin signaling with Wnt3a or GSK-3β inhibitor enhanced the proliferation and survival of bone sarcoma cells, whereas antagonism of this pathway with dnTCF4 or siLEF1 had the exact opposite effect." (PMID 25999350, 2015). "Activation of Wnt/β-catenin signaling with Wnt3a or GSK-3β inhibitor drives the proliferation of bone sarcoma cells, whereas downregulation of activated Wnt signaling with dnTCF4 or siLEF1 suppresses bone sarcoma proliferation and induces cell cycle arrest." (PMID 25999350, 2015). "Therefore, the biological function of GSK-3β in bone sarcomas remained to be elucidated and requires individual assessment in each type of tumors." (PMID 25999350, 2015). "In bone sarcoma SW1353 and U2OS cells, the GSK-3β inhibitor SB-216763 substantially upregulated active β-catenin while total β-catenin had no detected change, and enhanced reporter gene activity." (PMID 25999350, 2015).
Burkitt lymphoma (1 paper, 2022). A rare form of malignant mature B-cell non-Hodgkin lymphoma. "Consistent with a previous study, we found that TRAF3 co-immunoprecipitated with GSK3β in three BCL cell lines: BJAB, a Burkitt Lymphoma; Karpas 422, a Germinal Center B cell-like Diffuse Large B Cell Lymphoma (GCB DLBCL), and Dawo, a DLBCL not otherwise specified." (PMID 36291813, 2022).
carbon monoxide poisoning (1 paper, 2025). A poisoning that is caused by exposure to carbon monoxide. "Besides ferroptosis, previous researches have also demonstrated the neuroprotective roles of the Nrf2/GCLC and GSK-3β/Tau pathways in acute carbon monoxide poisoning." (PMID 40653468, 2025).
cardiac arrest (1 paper, 2021). Cessation of breathing and/or cardiac function. "Previous studies found that hypothermia could prevent hippocampal oxidative stress and apoptosis via the GSK‐3β/Nrf2/HO‐1 signaling pathway in a rat model of cardiac arrest‐induced brain damage." (PMID 34228907, 2021).
cartilage disease (1 paper, 2022). Softening and degeneration of the CARTILAGE. "Given the molecular mechanisms of GSK-3β in chondrogenic differentiation in inflammation, GSK-3β is a crucial target for the treatment of inflammation-induced cartilage disease." (PMID 36132167, 2022).
cerebral malaria (1 paper, 2021). A sequestration of Plasmodium falciparum in the brain, which can cause coma and/or seizures. "Furthermore, LiCl treatment restored long-term neurocognitive function in experimental cerebral malaria suggesting that the anti-malarial effect is attributed to the dysregulation of GSK3β." (PMID 33803419, 2021).
cervical squamous cell carcinoma (1 paper, 2023). A squamous cell carcinoma arising from the cervical epithelium. "GSK3β was involved in the development of cervical squamous cell carcinoma by negatively regulating the nuclear accumulation of Cyclin D1, while p21 and p27 jointly stabilize the Cyclin D1 protein by inhibiting its nuclear export." (PMID 37951919, 2023).
chlamydial infection (1 paper, 2022). "Phosphorylation-dependent inactivation of GSK3β also occurs during normal chlamydial infection and causes the accumulation of c-Myc protein, as GSK3β leads to a destabilization of c-Myc by phosphorylation on the threonine 58 and proteasomal degradation." (PMID 36155135, 2022).
chondrosarcoma (1 paper, 2019). A malignant cartilaginous matrix-producing mesenchymal neoplasm arising from the bone and soft tissue. "Increased β-catenin and phosphorylated GSK3β at serine 9 was observed following I3O treatment in RCS cells, a rat chondrosarcoma cell line, as well as in ATDC5 cells." (PMID 31515471, 2019).
choroidal melanoma (1 paper, 2021). Malignant tumor of melanocytes of the choroid. "Therefore, we considered that LiCl-induced apoptosis in human choroidal melanoma cells was GSK3β independent." (PMID 33557839, 2021).
chronic hepatitis (1 paper, 2019). An active inflammatory process affecting the liver for more than six months. "For instance, in patients with chronic hepatitis, inhibition of GSK3β by lithium exerts hepatoprotection through up-regulation of Nrf2 antioxidant response." (PMID 31349118, 2019).
chronic hepatitis B (1 paper, 2014). "Moreover, the activity of GSK3β was measured in the liver of chronic hepatitis B (CHB) patients and ALF patients." (PMID 24531650, 2014).
ciliopathy (1 paper, 2025). A genetic disorder of the cellular cilia or the cilia anchoring structures, the basal bodies, or of ciliary function. "The exact mechanism of how the ciliary WNT/GSK3β pathway contributes to cilia dynamics as well as the overall outcome of WNT signaling in ciliopathy conditions remains to be elucidated." (PMID 40483459, 2025). "It will now be crucial to explore how this WNT/GSK3β signaling route contributes to the overall WNT signaling outcome in ciliopathy models and examine its potential crosstalk with the HH pathway in relevant cases such as cancer and embryogenesis." (PMID 40483459, 2025).
Cirrhosis (1 paper, 2022). A chronic disorder of the liver in which liver tissue becomes scarred and is partially replaced by regenerative nodules and fibrotic tissue resulting in loss of liver function. "Another investigation demonstrated the abolishing of AKT-mediated phosphorylation of glycogen synthase kinase 3β (GSK3β) on Ser9 in cirrhosis compared to the normal cells." (PMID 36297027, 2022).
cleidocranial dysplasia (1 paper, 2007). "The cleidocranial dysplasia in heterozygous Runx2-deficient mice was significantly rescued by the genetic insufficiency of GSK-3β or the oral administration of lithium chloride, a selective inhibitor of GSK-3β." (PMID 17786208, 2007). "The cleidocranial dysplasia phenotype by the Runx2 insufficiency was significantly rescued not only by the genetic suppression of GSK-3β, but also by the oral administration of lithium chloride." (PMID 17786208, 2007). "Runx2+/− mice, a model for human cleidocranial dysplasia, showed delayed closure of the fontanelle and hypoplasia of the clavicle due to impaired bone formation, whereas Gsk-3β+/− mice had no such abnormalities." (PMID 17786208, 2007).
cognition (1 paper, 2020). Intellectual or mental process whereby an organism becomes aware of or obtains knowledge. "We found that lithium could reduce GSK3β activation, induced by SEV anesthesia, neural apoptosis and cognition impairment in rats." (PMID 31867790, 2020).
complication (1 paper, 2016). Any disease or disorder that occurs during the course of, or because of, another disease, treatment, or procedure. "For example, combining a therapy that inhibits GSK3β (to increase autophagy) with one that activates AMPK (to reduce inflammation and oxidative stress) may improve the prognosis for diabetic cardiovascular complications." (PMID 27534430, 2016).
Constipation (1 paper, 2022). Infrequent or difficult evacuation of feces. "Furthermore, the network pharmacology analysis showed that Akt1, Stat3, Mapk8, Hsp90aa1, Cat, Alb, Icam1, Sod2, and Gsk3b can be regarded as the core anti-constipation targets." (PMID 35408632, 2022).
cortical atrophy (1 paper, 2018). "Although the onset and patterns of cognitive symptoms and cortical atrophy present in SPG11 patients are markedly different from those observed in AD patients, our data suggest that GSK3β over-activation may be a common molecular denominator of both diseases." (PMID 30574063, 2018).
craniosynostosis (1 paper, 2019). Craniosynostosis is defined as the premature fusion of one or more cranial sutures leading to secondary distortion of skull shape resulting in skull deformities with a variable presentation. "Compound heterozygous Twist1(+/-)/Gsk3β(+/-) had a significantly higher frequency of craniosynostosis than predicted by the additive effects of each mutation alone (increasing from 35% in Twist1(+/-) and 15% in Gsk3β(+/-) to 94% in Twist1(+/-)/Gsk3β(+/-) compound heterozygotes)." (PMID 31442251, 2019). "In this study, we describe compound heterozygous mutant mice with genetically altered expression of Igf1 and Gsk3β and disinhibition of Runx2, that result in a significantly increased rate or severity of craniosynostosis when compared to mice with each genotype in isolation." (PMID 31442251, 2019). "In this manuscript we present data from mouse cross-breeding experiments designed to explore possible polygenic inheritance of craniosynostosis using Twist1/Igf1 and Twist1/Gsk3β compound heterozygotes to test hypotheses generated from our previous human expression data." (PMID 31442251, 2019). "While none of the Gsk3β(+/-)/Igf1(+/tg) mice that survived to P28 showed suture fusion, the reduced number of offspring with this genotype precludes our ability to define the true craniosynostosis rate." (PMID 31442251, 2019).
cutaneous melanoma (1 paper, 2022). A primary melanoma arising from atypical melanocytes in the skin. "Moreover, inhibition of GSK3β, which increased β-catenin and SNAIL activity, contributed to the invasion of NAV2-associated cutaneous melanoma cells." (PMID 35350242, 2022).
cystic kidney (1 paper, 2016). "Increased levels of GSK3β phosphorylation, β‐catenin, and cMyc expression in all cystic kidney samples demonstrate that activation of the Wnt/β‐catenin signaling pathway is another common feature of human ADPKD and Pkd1 cKO mice." (PMID 27356569, 2016).
developmental delay (1 paper, 2017). "This reduction in GSK3β activity may have contributed significantly to the beneficial effect of P021 on developmental delay in new-born period and AD-like memory deficit in adult life in Ts65Dn mice." (PMID 28368015, 2017).
diabetes insipidus (1 paper, 2022). A disorder characterized by excretion of large amounts of urine, accompanied by excessive thirst. "GSk3β is known to increase the risk of developing diabetes insipidus." (PMID 36362835, 2022).